GSK3B (glycogen synthase kinase 3 beta)
Diseases named in the same sentence as GSK3B in open-access papers (continued):
Sharing a sentence is not in itself a finding about the gene and the disease.
cancer (continued). "PP2A has been shown to activate GSK3β activity in cancer cells as well as neurons." (PMID 27534430, 2016). "Currently, GSK3B inhibitors are under clinical trial for the treatment of cancers, but these compounds could also be potential treatments for T2D." (PMID 26818947, 2016). "Inactivation of GSK-3β by phosphorylation at serine 9 and activation of PI3K/Akt, MAPK/ERK and β-catenin was associated with increased cell proliferation and apoptosis evasion during stepwise evolution of HBP carcinomas." (PMID 26902162, 2016). "In addition to CRC tissues, HCT116 cells also showed an increased expression of active β-catenin protein and a less abundant phosphorylated (Ser37) β-Catenin by inhibition of GSK3β relative to other tested cancer cell lines." (PMID 26060426, 2015). "Importantly, β-catenin, an established marker for GSK-3β inhibition, was shown to be involved in activation of hTERT transcription in cancer cell lines." (PMID 25618407, 2015). "Additionally in the presence of DC120 phosphorylation of AKT downstream targets such as FKHRL1 and GSK-3β were markedly decreased in cancer stem-like SP cells." (PMID 25749514, 2015). "As recently described, we suggest that GSK3β inhibition could represent a good strategy targeting the cross-regulation between these two pathways and may be a promising direction for future cancer therapy that needs to be better elucidated." (PMID 25738332, 2015). "GSK3β has various roles in cancer which even after years of study remain complex and controversial." (PMID 26556864, 2015). "Therefore, β-catenin phosphorylation and degradation via GSK3β activation constitute one of the anti-cancer action mechanisms of PI3K/Akt inhibitors." (PMID 26544726, 2015). "For cancer treatment, GSK-3β inhibition has been studied as a possible therapeutic strategy." (PMID 26292722, 2015). "Indeed, phosphorylated-GSK-3β expression is frequently associated with EMT (epithelial-mesenchymal transition), which promotes the dissemination of cancer cells from primary tumors." (PMID 24894011, 2014). "Alterations in GSK3β have been found in several cancer types [for details, see in Ref." (PMID 25478322, 2014). "GSK3β activation resulted from Akt inactivation in MTA-treated cancer cells." (PMID 24930764, 2014). "Both in normal and cancer cells, GSK3β inactivation, through Ser9 phosphorylation, may occur by stimulation of the PI3K/Akt and the MAPK pathways in response to several mitogens, including insulin and paracrine/autocrine IGFs." (PMID 24550888, 2014). "Previous reports have demonstrated the interaction between GSK3β and miRs in various human cancers." (PMID 24335145, 2014). "Studies have shown clear regulatory mechanisms of GSK3β activity in various cancer, however, that of GSK3β expression remains unclear in GBM." (PMID 25265336, 2014). "Moreover, we found that GSK-3β inhibition mainly acts on cancer stem/progenitor-like cells which were shown to be largely androgen-independent." (PMID 25344861, 2014). "Because we found that high TMEPAI activates downstream PI3K-Akt signaling that has the potential to increase Snail expression through the signaling intermediate GSK3β, our results provide an explanation for the invasive potential of triple negative cancer cells with amplified TMEPAI." (PMID 25352949, 2014). "In the present study, we also showed that GSK3β participated to cancer cell death induced by MTAs." (PMID 24930764, 2014). "Different roles in diseases have been identified for each isoform: for instance, GSK3β is overexpressed in many types of cancer including ovarian cancer, pancreatic cancer, colon cancer, etc; meanwhile, there are few reports on the role of GSK3α in cancer." (PMID 25010341, 2014). "We detected a significant reduction in the phosphorylation of GSK3β in anthocyanin-treated hepato-carcinoma cells, which might result in diminished β-catenin expression." (PMID 24666969, 2014).
cancer (continued). "Although GSK3β is a key regulator of cell polarization and migration during physiological processes such as tissue development and wound healing, very little is known about its role in the migration and invasion of cancer cells." (PMID 23408967, 2013). "No consistent changes were observed for the expression of EMT-related molecules in cancer cells treated with GSK3β inhibitor, in contrast to a previous study that found GSK3β inhibits EMT by phosphorylating and destabilizing snail, a transcriptional repressor of E-cadherin." (PMID 23408967, 2013). "GSK3β has been emerged as a molecular target for cancer therapy." (PMID 24312384, 2013). "This issue should be an important future task for cancer treatment targeting GSK3β." (PMID 23408967, 2013). "Importantly, both xanthatin and GSK3β inhibitors showed subtle cytotoxicity in normal cells, which further confirmed the high values of the therapeutic target in cancer therapy." (PMID 24312384, 2013). "GSK3β inhibition attenuated the survival and proliferation of cancer cells." (PMID 23408967, 2013). "Effects of GSK3β inhibition on cancer cell xenografts were also examined." (PMID 23408967, 2013). "Although the underlying mechanisms are yet to be understood, differential roles for GSK3β in normal and neoplastic cells could be advantageous for cancer treatment strategies that target this kinase." (PMID 23408967, 2013). "Cancer cell-derived GSK3β was active for phosphorylation of its substrate, β-catenin." (PMID 23408967, 2013). "Inhibition of GSK3β also enhanced the effect of ionizing radiation against cancer cells." (PMID 23408967, 2013). "The role of GSK-3β on NF-κB activation may also be mediated indirectly through inhibition of β-catenin, as cancer cells with high β-catenin levels are especially sensitive to TNF-induced death." (PMID 22675363, 2012). "Taken together, these results demonstrated that GSK3β could modulate LCRMP-1 activity through a phosphorylation-dependent manner to control cancer cell invasion." (PMID 22363707, 2012). "In addition, at least partly, the suppression of PI3K/Akt by HRT induces dephosphorylation of mTOR and GSK3β, resulting in the inhibition of cancer cell proliferation." (PMID 22899960, 2012). "All together, these data show that the oncogenic inactivation of GSK3β by the delE746-A750EGFR or E545KPIK3CA cancer proteins significantly increases nuclear β-catenin pool in response to GD and enhances β-catenin- and FOXO4-dependent expression of genes involved in antioxidant stress response." (PMID 22662165, 2012). "GSK3β is known to be involved in multiple pivotal signaling pathways and has been shown to play a role in development, cell polarity, insulin signaling, metabolic regulation, neurodegenerative disorders, and cancer." (PMID 23166798, 2012). "Another consideration is that chronic inhibition of GSK-3β could increase several transcription factors and β-catenin, which could contribute to the development of cancer." (PMID 21603026, 2011). "GSK3b inhibition increases WNT/beta catenin, associated with colon and other cancers." (PMID 21931595, 2011). "Lithium inhibition of GSK3β increases WNT/beta-catenin, known to be associated with cancer." (PMID 21931595, 2011). "GSK-3β has been shown to play a critical role in NF-κB-mediated survival of cancer cells." (PMID 21110852, 2010). "The differences in the roles of GSK3β depending on the type of cancer are quite interesting." (PMID 20537194, 2010). "Regarding the relation between GSK-3β and prognosis in human cancers, there have been few reports." (PMID 20704706, 2010). "Recent studies on natural compound GSK3β inhibitors suggest that this class of drugs may be promising for the regulation of certain cancers." (PMID 21143984, 2010). "GSK3β can promote or suppress growth in different types of cancer." (PMID 20537194, 2010). "However, GSK-3β is inactivated in cancer cells by phosphorylation at serine 9, a similar mechanism of GSK-3β inhibition by lithium." (PMID 21126356, 2010).
cancer (continued). "This discrepancy may, at least in part, comes from the differential role of GSK-3β in different cancer cell type as shown in earlier studies." (PMID 20704706, 2010). "GSK-3β protein is known to be overexpressed in human prostate, pancreatic, and colon carcinomas." (PMID 21110852, 2010). "Here we show that cell density and GSK-3β regulate cadherin-11 levels in cancer cells." (PMID 19274078, 2009). "It has been suggested that nuclear GSK-3β might contribute to NF-κB-mediated expression of anti-apoptotic molecules and cancer cell survival." (PMID 19920820, 2009). "Screening of several key proteins controlling cell cycle, development, metabolism, apoptosis and growth, including Erk, Akt, GSK3β, p16 and p14, Bcl-2, c-Myc, Nestin and Sox2, showed that downregulation of Bmi1 reduced GSK3β protein levels and induced differentiation in cancer cells." (PMID 19823589, 2009). "This possibility suggests that high levels of MAPK activity in cancer cells may make the requirement of GSK3β redundant for cyclin D1 phosphorylation at Thr286." (PMID 17205132, 2006). "Moreover, there is increasing evidence that aberrantly expressed GSK3B is involved in various cancer types and may promote cancer cell immortalization, proliferation, and invasion, while conferring resistance to radiation and chemotherapy agents." (PMID 41243969, 2025). "Moreover, the integration of GSK3β inhibitors in cancer immunotherapy presents a novel frontier." (PMID 41190025, 2025). "Therefore, we tested the hypothesis that β-lap and BV3 and BV5 could interfere with the action of CDKs, GSK3β, and other kinases for cancer therapy." (PMID 40573233, 2025). "Also, it is known that the inhibition of GSK3β has a therapeutic effect on 25 types of cancer." (PMID 40573233, 2025). "Empirical investigations have confirmed GSK-3β′s involvement in a wide spectrum of malignancies, including prostate, colorectal, gastric, pancreatic, liver, ovarian, osteosarcoma, leukemia, non-small cell lung, bladder, thyroid, glioma, kidney cancers, and other malignant tumors." (PMID 39156976, 2024). "Dysregulation of GSK3B in cancer may lead to uncontrolled cell growth." (PMID 38769413, 2024). "Aberrant nuclear localization of GSK-3β has also been linked to a negative clinical cancer outcome." (PMID 38886580, 2024). "Thus, cancer treatments targeting the activation of GSK3β could induce ROS accumulation, potentially leading to cancer cell death." (PMID 39596452, 2024). "Similarly, present evidence has also revealed that GSK-3β could improve cancer via regulating the NF-κB signaling pathway cascade via promoting the transcriptional activity of NF-κB in the nucleus." (PMID 36541814, 2023). "Additionally, snail is a downstream target of the AKT/GSK3β signaling pathway in cancer cells." (PMID 36670097, 2023). "Importantly, our results are supported by the hypothesis that NDRG1 has a different interplay with the same molecules in distinct cancers and cell types 8, namely TGFβ1, GSK3β, and NF-κB." (PMID 36594086, 2023). "Since GSK3β is involved in repressing Wnt/β-catenin signaling, but also in maintaining cell survival and proliferation via the NF-κB pathway, the inhibition of this dual kinase activity by lithium might have a positive effect on cancer hallmarks." (PMID 36836894, 2023). "This indicates that GSK-3β inhibitor can be used as an autophagy-targeted drug, and autophagy blockade has the potential to be an effective interventional strategy for addressing cancer progression and overcoming therapeutic resistance in addition to existing treatment." (PMID 37366889, 2023). "The expression of GSK3B was significantly inversely linked to the naive CD4+ T cells, memory B cells, NK T cells, and Tregs infiltration, and significantly positively linked to macrophage, neutrophil, cancer-associated fibroblast (CAFs), B cell plasma and activated mast cell infiltration." (PMID 36743929, 2022).
cancer (continued). "Thus, we employed the immunoblot analysis to delineate whether LECT2-modulated cancer stemness/EMT/VEGF pathways is mediated GSK3β/β-catenin signaling." (PMID 36055405, 2022). "Therefore, it is reasonable to use GSK-3β inhibitors to target malignant tumors." (PMID 35836256, 2022). "However, recent reports have suggested that GSK3B is a positive regulator of cancer progression." (PMID 35096583, 2021). "Interestingly, GSK-3β appears to play different roles in various cancer types." (PMID 34966427, 2021). "Interestingly, 9-ING-41, a novel GSK3B inhibitor developed by Actuate Therapeutics, is currently undergoing phase 1 and phase 2 trials as a single agent and in combination with cytotoxic agents, in patients with refractory cancers, including CRCs." (PMID 34065438, 2021). "However, we observed β-catenin independent response via p-Gsk3β in PC; this unanticipated data may be due to different cancers and cell origins." (PMID 34206370, 2021). "Therefore, targeting AKT/GSK-3β/β-catenin is a novel approach in cancer treatment." (PMID 33777320, 2021). "The expression of p-AKT, p-GSK3β, and p-DNA-PKcs decreased in the knockdown group after radiotherapy, suggesting that cancer-IgG could affect radiotherapy resistance by mediating double-strand breaks damage repair in LUAD cells through the PI3K/AKT/DNA-PKcs pathway." (PMID 34150640, 2021). "However, a prolonged activation of GSK3β promoted a defect in epithelial regeneration and a resistance to chemotherapy of leukemic cells, paving the way to chronic inflammatory diseases and to cancer resurgence, respectively." (PMID 33498808, 2021). "Therefore, GSK-3β inhibition may repress the activity of NF-κB, resulting in the downregulation of various genes involved in cancer progression, such those coding for anti-apoptotic proteins." (PMID 32526891, 2020). "However, this protein might function as a tumour suppressor or oncogene in different cancer types, and the use of GSK3-β inhibitors for cancer treatment needs further study." (PMID 31963420, 2020). "However, recent evidence suggests that the selective inhibition of GSK3α and GSK3β activity may shed light on the role of each paralog and also open new avenues for developing specific therapeutic strategies for each type of cancer." (PMID 33339170, 2020). "Therefore, further study on the role of GSK3β in cancer is still needed." (PMID 32158616, 2020). "It has some anti-cancer properties which may be mediated by GSK-3β and WNT/β-catenin." (PMID 32365809, 2020). "Indeed, the PAR2-GSK3β pathway controlling ISC survival may pave the way to inflammation and cancer where GSK3β is overactivated." (PMID 31492202, 2019). "Therefore, GSK3-β inhibition as a therapy in cancer cells could be promoting undesired survival via Claspin stabilization and Chk1 activation." (PMID 31362447, 2019). "Interestingly, as Chk1, GSK3-β is a therapeutic target in cancer." (PMID 31362447, 2019). "Interestingly, according to previous studies, GSK3β has dual effects in different types of cancer." (PMID 31744046, 2019). "However, it remains unclear whether there is a direct and causal relationship between β-catenin accumulation and facilitation of osteogenesis via GSK-3β inhibition leading to cancer suppression." (PMID 31698687, 2019). "Therefore, the conflict of GSK3β’s functions might disturb the effect of NLIPMT in different types of cancer." (PMID 31744046, 2019).
cancer (continued). "However, little is known about whether and how GSK3β mediates mechanistic processes in the spindle apparatus and centrosomes during mitosis in cancer cells." (PMID 29568361, 2018). "GSK3β is a serine/threonine protein kinase that plays a key role in signal transduction during processes such as cell cycle progression, proliferation and inflammation through phosphorylation of target proteins and shows altered activity in a number of cancers." (PMID 27907888, 2017). "The alterations of phosphorylation status of AKT and its substrate GSK3β, up-regulation of pro-apoptotic regulators including caspase-3, caspase-9 and PARP, and up-regulation of cell cycle regulator p27, were implicated in the biological activity of OPCML in cancer cells." (PMID 28407749, 2017). "In addition to their effects on GSK3β, lithium and valproate induced autophagy via inhibition of inositol monophosphatase and modulation of oxidative stress, respectively, resulting in cancer therapeutic effect." (PMID 28423558, 2017). "The extremely low false discovery rates show that these statistical enrichments could not have occurred by chance, implying that the lithium effect on these pathways, exerted through its inhibition of GSK3B, indeed has significant implications for cancer incidence and therapy." (PMID 29127487, 2017). "Thus, phosphorylation of GSK3β on Ser389 in response to chemotherapy or radiotherapy may have implications in the treatment of cancer." (PMID 26822034, 2016). "Thus pathways that can modulate GSK3β axis are important targets for cancer drug development." (PMID 27602497, 2016). "It is still not clear if mitochondrial GSK3β is associated with neurodegerative diseases or cancer." (PMID 27087918, 2016). "Consistently, clinical database analysis revealed a poor survival outcome for cancer patients with high integrin β3 mRNA expression, suggesting that the integrin β3-Akt-GSK3β signaling axis could be used as an important therapeutic target for preventing malignant cancer progression." (PMID 27015122, 2016). "Taken together, these conclusions support the idea that use of small molecule inhibitors targeting GSK3β, molecules proven safe and effective in other unrelated cancers, may be a viable route for the development of novel therapies for ARMS through animal studies and pre-clinical trials." (PMID 25821947, 2015). "Our present findings further extend the function of GSK3β in the regulation of ciliogenesis, support a positive role of GSK3β in the regulation of cilium assembly, and may have implications for understanding why rapidly-proliferating cells (such as cancer cells) often lose their cilia." (PMID 25860027, 2015). "However, in certain cancers GSK3β may be also inactivated by the occurrence of molecular abnormalities, including the expression of constitutively activated Akt3 and PTEN inactivation." (PMID 24550888, 2014). "However, the role of GSK3β differs in different cancers, and the precise role of GSK3β in NSCLC remains unclear." (PMID 24618715, 2014). "However, cancer cells cannot operate the Axin/APC/GSK-3β complex by overexpression of Wnt-1." (PMID 23982808, 2013). "We investigated whether GSK3β contributes to cancer cell survival and proliferation." (PMID 23408967, 2013). "Therefore, restoration of Rb ability to bind to E2F following GSK3β inhibition may sensitizes cancer cells to gemcitabine by affecting RR expression." (PMID 23408967, 2013). "Therefore, a role for GSK3β in regulating NF-κB activity in cancer cells remains controversial." (PMID 23408967, 2013). "In addition to the pathologic roles of GSK3β in cancer cell survival and proliferation GSK3β may influence critical biological properties of cancer cells, such as their dependence on glycolysis and invasive ability associated with EMT." (PMID 24212624, 2011).